MTAP (methylthioadenosine phosphorylase)
Diseases named in the same sentence as MTAP in open-access papers (continued):
Sharing a sentence is not in itself a finding about the gene and the disease.
tumor (continued). "They initially proposed MTAP as a potential tumor suppressor, because it was the only homozygously deleted gene, and its copy number was significantly correlated with mRNA expression." (PMID 38548861, 2024). "In order to simulate the early stage of tumor, we inoculated the normal expression cells of MTAP in the lower layer while the deletion cells of MTAP in Transwell chambers." (PMID 39711357, 2024). "“Combined inhibition of MTAP and MAT2a mimics synthetic lethality in tumor models via PRMT5 inhibition” JBC submission, September 2023." (PMID 38000655, 2024). "Genomic analysis using the FoundationOne® companion diagnostic revealed a low-tumor mutational burden (TMB), microsatellite stable, and the loss of the methylthioadenosine phosphorylase (MTAP) gene (MTAP loss)." (PMID 38190036, 2024). "MTAP-loss PDAC, IHCC, and CRC had a lower prevalence of microsatellite instability or elevated tumor mutational burden." (PMID 38330461, 2024). "Here, synthetic lethality is induced systemically and is therefore a mimic of genetic MTAP−/− in the tumor tissue." (PMID 38000655, 2024). "Coincidentally, these data proved that SDMA modification in neoplastic cells from MTAP‐non‐expressing tumors was reduced by ∼50% compared with MTAP expressing tumors across tumor types." (PMID 39711357, 2024). "Due to specific accumulation of MTA in MTAP-del tumor cells, the new action mode make it possible to specially target tumor cells but spare normal cells with a small molecule." (PMID 39655075, 2024). "MTAP is required for adenosine monophosphate and methionine salvage and has a tumour suppressive effect in multiple cancers." (PMID 37504251, 2023). "There is growing evidence that MTAP can control tumor invasion and migration through many signaling mechanisms." (PMID 36913304, 2023). "Both MTA uptake or PRMT5 inhibitor resulted in decreased cell viability in MTAP-deleted tumor cells compared with MTAP-expressing tumor cells." (PMID 37091983, 2023). "Following the concepts of synthetic lethality, when MTAP is lost in a tumor cell, MTA will build up inside the cell leading to more suppression of PRMT5, thereby increasing their vulnerability to inhibition." (PMID 36913304, 2023). "TNG908 demonstrated antineoplastic activity against MTAP-null selective tumors in various xenograft models, including tumor regression in a model representing NSCLC and cholangial and urothelial carcinomas." (PMID 38136401, 2023). "Most tumor cells have MTAP, P16 and other tumor suppressor genes located on 9P21 such as CDKN2A and CDKN2B making it a poor target for therapeutic regimens." (PMID 36913304, 2023). "Studies have shown that MTAP acts as a suppressor gene and inhibits the proliferation, migration and invasion of tumor cells." (PMID 37277447, 2023). "MTAP downregulation also promotes tumor metastasis by activating the GSK3B/slug/E-cadherin axis in esophageal squamous cell carcinoma." (PMID 36913304, 2023). "In this study, we evaluated the clinical outcomes of patients with UC who were treated with pemetrexed stratified by tumor MTAP protein expression as a surrogate marker for 9p21 status." (PMID 35379845, 2022). "Functional studies showed that MTAP was able to suppress both in vitro and in vivo tumorigenic ability of BC cells, including migration, invasion, angiogenesis, tumor growth and metastasis in nude mice with orthotopic xenograft tumor of BC." (PMID 35541910, 2022). "The MTAP/CDKN2A locus encompasses two functional tumour suppressor genes, CDKN2A and CDKN2B, that are known to play a role in familial and sporadic melanoma risk, as well as a number of other genes with potential involvement in this disease." (PMID 35357426, 2022). "We indeed found that the primary BC tumors removed from the MTAP knockdown group had abundant tumor blood vessels compared with the control group." (PMID 35541910, 2022).
tumor (continued). "To further confirm our hypothesis that tumor MTAP deficiency leads to antifolate sensitivity, we carried out in vivo experiments in xenograft models of UC, which demonstrated that the MTAPprof HT-1376 tumor was resistant to pemetrexed whereas the MTAPdef UM-UC-3 tumor was sensitive to pemetrexed." (PMID 35379845, 2022). "While all these differences in the tumor immune profile may be linked or regulated by a similar mechanism and warrant additional investigation, further work presented in this study focuses on macrophage regulation as a model for MTAP deficiency regulating the immune microenvironment." (PMID 35264604, 2022). "Taken together, these results suggested that downregulation of MTAP promoted the tumor progression and metastasis in BC." (PMID 35541910, 2022). "In this study, our TMA analysis confirmed that MTAP was abundantly expressed in non-tumor tissues but down-regulated in 41% (35/85) of BC tumor tissues." (PMID 35541910, 2022). "MTAP expression instead has been analysed in a cohort of pediatric and adult PA samples and resulted lost in tumours arisen in the cerebral hemispheres." (PMID 35715818, 2022). "Accumulating evidence suggests that MTAP can regulate tumor migration and invasion via different signaling pathways." (PMID 35541910, 2022). "As compared to the control group, H&E results showed heavy tumor burden while IHC results showed stronger MTAP staining in both lungs and tumors of the MTAP-knockdown group." (PMID 35541910, 2022). "In culture, MTAP-deleted tumor cells excrete large amounts of MTA into the media and have increased intracellular MTA concentrations." (PMID 35963436, 2022). "Transcriptions of CDKN2A, CDKN2B, CDKN2B_AS1, and MTAP were included because these genes are located at 9p21.3, and they are also potential tumor suppressors." (PMID 36313281, 2022). "To validate that the phenotype induced by exogenously administered MTA is relevant to the amount of MTA produced by tumor cells, we generated an isogenic MTAP-null derivative of the murine GBM cell line CT-2A." (PMID 35264604, 2022). "The next step in this phase I study is to evaluate AG-270 in combination with taxane-based chemotherapy, which demonstrated synergistic antiproliferative effects in preclinical MTAP-null tumor models." (PMID 34981784, 2022). "In this study, we provide multiple lines of evidence to link MTAP loss, one of the most common genetic/epigenetic events in GBM, to changes in the tumor immune microenvironment." (PMID 35264604, 2022). "Efforts have been made to target methionine metabolism in tumors with deletion of methylthioadenosine phosphorylase (MTAP), which is often co-deleted with the tumor suppressor CDKN2A." (PMID 34981784, 2022). "In the clinical proteomic tumor analysis consortium (CPTAC) database, the levels of MTAP protein in primary tumor tissues (n=125) were significantly lower than that in normal breast tissues (n=18, P=1.41E-11)." (PMID 35541910, 2022). "Both groups have independently reported that the combination of PRMT1 and PRMT5 inhibition has synergistic effects on tumour cell growth, at least partly mediated by methylthioadenosine phosphorylase (MTAP)." (PMID 33404912, 2021). "PD-L1 IHC staining in tumor cells was performed in a subset of patients, showing a trend of decreased fraction of PD-L1 positivity in tumors of the MTAP- group." (PMID 34556668, 2021). "Copy number analysis (using methylation array data and WGS) of both the patient and PDX tumours revealed hemizygous loss of chromosome 1p and homozygous deletions on chromosome 9p including a segment containing CDKN2A/B, MTAP and multiple interferon genes." (PMID 33053751, 2020). "Although Hansen and colleagues provided the first evidence for relevance of MTAP loss in stemness-induction in GBM, their study also failed to account for a wide range of factors known to influence tumor growth, migration, invasion, and resistance to therapy." (PMID 32093414, 2020).
tumor (continued). "Regarding tumor heterogeneity, we have shown in our study that MTAP and CDKN2A genomic pattern when analyzed by FISH can be a mixture of retained (no loss), homozygous or hemizygous loss signal patterns within one tumor." (PMID 33304846, 2020). "The tumor-suppressive function of MTAP in RCC has been established, but its molecular contribution has yet to be elucidated." (PMID 30701095, 2019). "MTAP staining was inversely correlated with tumor grade and gradually decreased in higher-grade RCC (p < 0.0001)." (PMID 30701095, 2019). "Chromosome 9p contains numerous tumor-associated genes, such as PAX5 at 9p13.2, CDKN2A, CDKN2B, MTAP, IFN, MLLT3, PTPLAD2 at 9p21.3, and JAK2 at 9p24.1." (PMID 31168295, 2019). "Next, we demonstrate the mechanisms of MTAP-mediated tumor suppression via the utilization of a phospho-RTK antibody array screen and identify IGF1R as a driver pathway in MTAP-deficient RCC." (PMID 30701095, 2019). "MTAP is responsible for the breakdown of S-methyl-5′-thioadenosine (MTA) and, because of MTAP deficiency, MTA levels can increase in the tumor microenvironment." (PMID 30076128, 2018). "Some tumours contain more intensities as +/− indicating that samples showed different degrees of MTAP expression even though in some cases the staining was weak." (PMID 30123503, 2018). "This study also demonstrated a tumor suppressive role for MTAP in cell growth and invasion, suggesting that it plays a role in GC progression." (PMID 29190909, 2017). "The second transcript (transcript 2) from the same tumor showed fusion involving exon 6 of MTAP and exon 6 of ANRIL; however, the end of the transcript remains to be determined." (PMID 26909863, 2016). "Several research groups have shown that MTAP acts as a tumor suppressor, and some therapeutic approaches were proposed based on a tumors ́ MTAP status." (PMID 26751376, 2016). "In one tumor, we detected fusion transcript similar to the one detected in MaMel-95 cell line involving exon 6 of MTAP and exon 5 of ANRIL with latter contributing three amino-acid residues." (PMID 26909863, 2016). "This variation between MTAP+/+ cells and tumor MTAP−/− cells led to several studies showing that MTAP−/− cells are more sensitive to inhibitors of de novo purine synthesis." (PMID 25917288, 2015). "These genes are localised close to known cyclin-dependent kinase inhibitors and tumour suppressors CDKN1C and CDKN2A/B, respectively, but both FAF1 and MTAP have recently been proposed to harbour tumour suppressor activity in their own right." (PMID 24548782, 2014). "Re-expression of MTAP in MTAP deleted MCF-7 breast cells results in loss of anchorage-independent growth in vitro and loss of tumor formation in vivo." (PMID 25387827, 2014). "Because ODC is a known oncogene, these findings suggested a possible mechanism for MTAP’s tumor suppressor effects." (PMID 25387827, 2014). "The xenografts reexpressing MTAP exhibited a significantly small average tumor volume from Day 7 until sacrifice on Day 30, on which the excised specimens were evidently larger and heavier in the controls than were those in the MTAP-reexpressing group." (PMID 25426549, 2014). "We found that the tumors excised from mice injected with M− cells had a 70% reduction in MTAP activity, indicating that the majority of cells in the tumor were derived from the injected M− cells." (PMID 25387827, 2014). "To elucidate the mechanism by which MTAP inhibits tumor formation, we have reintroduced MTAP into MTAP-deleted HT1080 fibrosarcoma cells." (PMID 25387827, 2014). "The in vivo inhibitory effect of MTAP on tumor growth was analyzed in NMFH-2 xenografts exhibiting ectopic MTAP reexpression versus empty controls." (PMID 25426549, 2014). "MTAP (DriverNet rank 3) and known tumor-suppressor CDKN2A (DriverNet rank 4) are known to be co-deleted and they were observed as such in our analysis." (PMID 23383675, 2012).
tumor (continued). "Many studies also reported MTAP function as a tumor suppressor gene and described an inverse correlation between MTAP protein levels and the progression of various tumors." (PMID 19214202, 2009). "A shared function of the neighbouring genes CDKN2A/2B and MTAP is the regulation of cell proliferation/tumor suppression." (PMID 19214202, 2009). "Our strategy involves two agents: a purine or pyrimidine analog toxic to both MTAP-negative tumor cells and MTAP-positive normal cells, and a second agent that protects the normal cells." (PMID 19478948, 2009). "Hemizygous deletion of the region harbouring the CDKN2A and CDKN2B loci was identified in two tumours by means of fluorescent in situ hybridisation and MTAP was present by immunostaining in all but one tumour analysed." (PMID 15305192, 2004). "When interpreted alongside p16 and MTAP, PRAME may further enhance diagnostic precision, particularly in deep penetrating neoplasms or spitzoid lesions with ambiguous features." (PMID 41596618, 2026). "Methylthioadenosine phosphorylase (MTAP), an enzyme related to tumor aggressiveness, may interact with oxidative and metabolic stress pathways relevant to tumor progression." (PMID 41750579, 2026). "This gradient of expression suggested that MTAP inactivation may contribute not only to tumor development but also to disease progression." (PMID 41596618, 2026). "First‐generation PRMT5 inhibitors such as GSK3326595 do not distinguish normal cells from MTAP‐deficient tumour cells." (PMID 41537447, 2026). "As noted, inhibitors targeting PRMT5‐MTA exhibit SL in MTAP‐deleted tumours." (PMID 41537447, 2026). "In this section, we will explore the different therapeutic targets identified over time, beginning with the recently discovered PRMT5/methionine adenosyltransferase 2A (MAT2A) axis and then tracing back to earlier targets that have shaped our understanding of MTAP-deleted tumor vulnerabilities." (PMID 41439984, 2025). "Further studies focusing on the interplay between WT and MTAP-deleted cells could provide more insights into the tumor’s biology." (PMID 39983717, 2025). "The relationship between 9p21 deletion and tumor phenotype was similar to that seen for MTAP IHC." (PMID 39668577, 2025). "However, some deletions can result in reduced MTAP protein expression, which is detected in tumor cells, but the staining strength is lower than in cells without MTAP gene deletion." (PMID 41465382, 2025). "Noninterpretable tumors were caused by insufficient hybridization (FISH), absence of MTAP immunostaining of both tumor cells and stroma cells (IHC), lack of unequivocal tumor cells on the TMA spots, or absence of entire tissue spots on the TMA." (PMID 39668577, 2025). "Homozygous MTAP deletion results in the loss of MTAP protein in tumor cells, which corresponds with a negative IHC staining." (PMID 41465382, 2025). "Homozygous co‐deletions of MTAP occur in 80–90% of CDKN2A deleted tumor cells." (PMID 39668577, 2025). "Although not many studies have made the comparison between MTAP-null and MTAP-WT tumors, there is still enormous potential in using methionine restriction as a technique to inhibit MTAP-null tumor growth as the methionine salvage pathway is significantly impacted in these tumors." (PMID 41439984, 2025). "Additionally, MTAP false positive detection can occur in tissues with few tumor cells due to intratumoral lymphohistiocytic infiltrates." (PMID 41439984, 2025). "In the same study, our MTAP IHC assay had been extensively validated according to the guidelines of the international working group for antibody validation and resulted in a 90-100 % concordance with homozygous deletion depending on the tumor type." (PMID 40554389, 2025). "Interestingly, our analysis also revealed two cases showing a completely preserved MTAP expression (100% of positive tumour cells), even though with a significant rate (>20%) of CDKN2A homozygous deletion by FISH." (PMID 40566743, 2025).
tumor (continued). "Furthermore, MTAP-deficient tumors exhibit intracellular and extracellular MTA accumulation in many different tumor types in vitro." (PMID 41439984, 2025). "A key finding of this study is that when methionine was restricted in a setting with MTAP deletion or inhibition combined with PARP inhibition, this triple-punch approach enhanced MTAP inhibitor–PARPi, synergy, leading to cell death and a decrease in tumor volume." (PMID 40590221, 2025). "Therefore, inhibiting MAT2A can serve as a potential therapeutic approach to suppress tumor growth, especially in cancers that lack MTAP." (PMID 40450009, 2025). "Deletion of the MTAP gene is one of the most common genetic abnormalities found in neoplasm cells." (PMID 41465382, 2025). "However, more MTAP-loss tumors were observed to be of East Asian (EAS) genomic ancestry within PDAC (4.4% vs 3.2%, P = .005) and IHCC (6.4% vs 4.3%, P = .036) tumor groups, compared with MTAP-intact." (PMID 38330461, 2024). "In other words, MTAP deletion sensitizes tumor cells to PRMT5 inhibition." (PMID 39711357, 2024). "Additionally, MTAP is reported to have tumor-suppressor functions unrelated to its enzymatic functions when reintroduced to tumors." (PMID 38000655, 2024). "Although the tumor cells showed only MTAP loss, we concluded that there were no druggable mutations." (PMID 38190036, 2024). "Indeed, single-agent TNG908 was able to drive tumor regressionsin the LU99 MTAP-deleted xenograft model, which highlightsthe potential for TNG908 to drive meaningful clinical responses in MTAP-deleted tumors while maintaining a large therapeuticindex." (PMID 38595098, 2024). "Collectively, these results indicate the potential of MTAP and p16 IHC as useful surrogate markers of CDKN2A HD in EPN-ZFTA, and tumor-associated macrophages, including the M2 type, may contribute to its immune microenvironment." (PMID 37322295, 2023). "Also of interest was the 9p21 locus, which contains the prominent tumor suppressor CDKN2A, MTAP, as well as a cluster of IFN genes and has been linked to ICI resistance in pan-tumor studies." (PMID 36977461, 2023). "Moreover, MTAP-deleted tumor cells exhibit greater sensitivity to methionine depletion and to the inhibitors of purine synthesis." (PMID 37091983, 2023). "The effects of CDKN2A/B deletion on tumour development may also be mediated, at least in part, by co-deletion of adjacent genes in the 9p21 region, such as MTAP, IFNA1, IFNB1, and ANRIL." (PMID 37504251, 2023). "MTAP loss in MTAP-expressing tumor cells results in increased sensitivity to PRMT5 inhibition, while MTAP re-expression in MTAP-deleted tumor cells could rescue PRMT5 reliance." (PMID 37091983, 2023). "MTAP deficiency, as a genetic alteration in GBM, mediates tumor cell response to DNA damage." (PMID 37091983, 2023). "MTAP deletion without CDKN2A co-deletion did not occur in any of the PM tumor samples, and loss of MTAP expression occurred exclusively in conjunction with loss of p16 labeling." (PMID 37894345, 2023). "MTAP has been found to exert its anti-tumor effects on tumor initiation and metastasis." (PMID 37091983, 2023). "However, in CRC, MTAP expression is upregulated by LEF/TCF/β-catenin in parallel with tumor progression and cell dedifferentiation." (PMID 36831453, 2023). "Additionally, in vivo studies verified that MRTX1719 demonstrates potent and enduring inhibition of PRMT5 in a MTAP-deleted tumor xenograft model, reducing its SDMA activity." (PMID 38136401, 2023). "MTAP is a metabolic enzyme that functions in the salvage pathway of adenine and methionine, and loss of MTAP results in the accumulation of its direct substrate, methylthioadenosine (MTA), which can be released into the tumor environment." (PMID 35264604, 2022). "As anticipated, vascular density quantification revealed that MTAP knockdown could induce more tumor vessels." (PMID 35541910, 2022). "The 2FA + MTA combination has prohibited the tumor growth in MTAP deleted tumors." (PMID 36572880, 2022).